DYNC1LI2 (dynein cytoplasmic 1 light intermediate chain 2)
Description:
Acts as one of several non-catalytic accessory components of the cytoplasmic dynein 1 complex that are thought to be involved in linking dynein to cargos and to adapter proteins that regulate dynein function. Cytoplasmic dynein 1 acts as a motor for the intracellular retrograde motility of vesicles and organelles along microtubules. May play a role in binding dynein to membranous organelles or chromosomes.
Synonyms: DNCLI2; LIC2
Tractability: Small molecule: a structure with a bound ligand is known. PROTAC: ubiquitination databases record sites on it; its protein half-life has been measured.
Gene: Protein-coding gene on chromosome 16 (66,720,893 to 66,751,836, reverse strand). Ensembl gene ENSG00000135720.
Subcellular location: Cytoplasm, cytoskeleton
Subcellular location (Human Protein Atlas): Centrosome; End piece; Cytosol
Pathways (Reactome):
Cell Cycle: Amplification of signal from unattached kinetochores via a MAD2 inhibitory signal; EML4 and NUDC in mitotic spindle formation; Mitotic Prometaphase; Resolution of Sister Chromatid Cohesion; Separation of Sister Chromatids
Vesicle-mediated transport: COPI-independent Golgi-to-ER retrograde traffic; COPI-mediated anterograde transport
Autophagy: Aggrephagy
Cellular responses to stimuli: HSP90 chaperone cycle for steroid hormone receptors (SHR) in the presence of ligand
Disease: HCMV Early Events
Immune System: MHC class II antigen presentation
Signal Transduction: RHO GTPases Activate Formins
Gene Ontology:
Molecular function: dynein heavy chain binding; identical protein binding
Biological process: microtubule cytoskeleton organization; microtubule-based movement; positive regulation of intracellular transport; cellular response to nerve growth factor stimulus
Cellular component: centrosome; cytoplasmic dynein complex; membrane; cytosol; male germ cell nucleus; cytoskeleton; kinetochore; late endosome
Genetic constraint (gnomAD): Loss-of-function variants: 19 observed, 58.86 expected, observed/expected ratio (o/e) 0.32, 90% interval 0.22 to 0.47. The upper end of that interval is the gene's LOEUF score, 0.47, which puts it in group 2 of 6, group 1 being the genes least tolerant of losing a copy. Missense variants: 470 observed, 626.56 expected, observed/expected ratio (o/e) 0.75, 90% interval 0.69 to 0.81. Synonymous variants: 256 observed, 240.77 expected, observed/expected ratio (o/e) 1.06, 90% interval 0.96 to 1.18.
Homologues: Orthologues: macaque DYNC1LI2 (99% identical), dog DYNC1LI2 (98% identical), guinea pig DYNC1LI2 (98% identical), pig DYNC1LI2 (98% identical), rat Dync1li2 (97% identical), mouse Dync1li2 (97% identical), rabbit DYNC1LI2 (97% identical), chimpanzee DYNC1LI2 (97% identical), tropical clawed frog dync1li2 (76% identical), zebrafish dync1li2 (76% identical), Drosophila melanogaster Dlic (45% identical), Caenorhabditis elegans dli-1 (29% identical). Paralogues in human: DYNC1LI1 (66% identical).
Diseases named in the same sentence as DYNC1LI2 in open-access papers:
DYNC1LI2 is named in the same sentence as 5 diseases in open-access papers, as found by Europe PMC text mining. Sharing a sentence is not in itself a finding about the gene and the disease. The quoted sentences say what the papers report.
cystine disease (2 papers, 2022). "Expression of DYNC1LI2 (LIC2) preserves LAMP-2A and CMA activity, cell homeostasis, and the localization of LRP2/megalin in cystinotic proximal tubular cells in cystine disease." (PMID 36187470, 2022).
autism (1 paper, 2025). Persistent deficits in social interaction and communication and interaction as well as a markedly restricted repertoire of activity and interest as well as repetitive patterns of behavior. "Interestingly, four related proteins, DYNC1I1, DYNC1LI1, DYNC1LI2 and DYNLRB1 were also reduced significantly in cerebellar vermis of children with autism." (PMID 40779003, 2025).
prostate carcinoma (1 paper, 2022). A carcinoma that arises from epithelial cells of the prostate gland. "The HPA database suggested that C18orf25, DYNC1LI2, SYNJ1, MAPK1, and ARID4B are highly expressed in normal tissues, and CLOCK, SETD2, ZNF654, XIAP, MIS18BP1, and MBTPS2 are highly expressed in prostate cancer tissues." (PMID 36249009, 2022).
cancer (1 paper, 2021). A tumor composed of atypical neoplastic, often pleomorphic cells that invade other tissues. "Functional gene clusters shared among cancer types include DYNC1LI2/I2/H1 that encode different components of the cytoplasmic dynein 1 complex and PPP1CC/1CA/2CB/2CA that encode subunits of protein phosphatase enzymes." (PMID 34620211, 2021).
tumor (1 paper, 2022). "Moreover, C18orf25, NUP160, DYNC1LI2, SYNJ1, MAPK1, and CLOCK were lowly expressed in tumor tissues." (PMID 36249009, 2022).